TRBV6-8 (T cell receptor beta variable 6-8)
Description:
V region of the variable domain of T cell receptor (TR) beta chain that participates in the antigen recognition. Alpha-beta T cell receptors are antigen specific receptors which are essential to the immune response and are present on the cell surface of T lymphocytes. Recognize peptide-major histocompatibility (MH) (pMH) complexes that are displayed by antigen presenting cells (APC), a prerequisite for efficient T cell adaptive immunity against pathogens. Binding of alpha-beta TR to pMH complex initiates TR-CD3 clustering on the cell surface and intracellular activation of LCK that phosphorylates the ITAM motifs of CD3G, CD3D, CD3E and CD247 enabling the recruitment of ZAP70. In turn ZAP70 phosphorylates LAT, which recruits numerous signaling molecules to form the LAT signalosome. The LAT signalosome propagates signal branching to three major signaling pathways, the calcium, the mitogen-activated protein kinase (MAPK) kinase and the nuclear factor NF-kappa-B (NF-kB) pathways, leading to the mobilization of transcription factors that are critical for gene expression and essential for T cell growth and differentiation. The T cell repertoire is generated in the thymus, by V-(D)-J rearrangement. This repertoire is then shaped by intrathymic selection events to generate a peripheral T cell pool of self-MH restricted, non-autoaggressive T cells. Post-thymic interaction of alpha-beta TR with the pMH complexes shapes TR structural and functional avidity.
Synonyms: TRBV68; TCRBV13S7P; TCRBV6S8
Gene: T-cell receptor variable (V) gene on chromosome 7 (142,507,382 to 142,507,810, forward strand). Ensembl gene ENSG00000253534.
Subcellular location: Cell membrane
Gene Ontology:
Biological process: cell surface receptor signaling pathway
Cellular component: plasma membrane
Homologues: Paralogues in human: TRBV6-5 (88% identical), TRBV6-7 (87% identical), TRBV6-6 (86% identical), TRBV6-1 (85% identical), TRBV6-2 (82% identical), TRBV6-4 (71% identical), TRBV10-2 (61% identical), TRBV10-1 (57% identical), TRBV10-3 (56% identical), TRBV27 (56% identical), TRBV19 (51% identical), TRBV28 (50% identical), and 39 more.